FAP (fibroblast activation protein alpha)
Diseases named in the same sentence as FAP in open-access papers (continued):
Sharing a sentence is not in itself a finding about the gene and the disease.
metastatic cancer (10 papers, 2017 to 2025). A carcinoma which has spread from the original site of growth to another anatomic site. "A dose-escalation study of [177Lu]Lu-FAPI-46 in 18 patients with FAP-expressing inoperable or refractory metastatic cancers demonstrated good tolerance." (PMID 41049848, 2025). "Next, the FAP expression in primary versus liver metastases was evaluated in matched primary and metastatic cancers." (PMID 39335130, 2024). "One of the first anti-FAP drugs, the anti-FAP antibody Sibrotuzumab (also known as F19 and BIBH 1) exhibited a good safety profile in patients with FAP-positive advanced or metastatic cancers in a Phase I trial." (PMID 38562556, 2024). "FAP+CAFs were significantly enriched in metastatic cancer samples, and their higher abundance was correlated with the worse overall survival in NSCLC patients." (PMID 38459511, 2024). "More specifically and importantly, COL1A1, COL1A2, and FAP were all highly expressed in metastatic cancer tissues, possibly indicated a higher chance of metastasis when abnormally expressed, which have not been reported before." (PMID 39034310, 2024). "The study was a single-arm prospective trial that evaluated the ability of a novel imaging agent gallium-68-labeled (68Ga-) FAP-2286 (68Ga-FAP-2286) to detect metastatic cancer in adults with solid tumors using 68Ga-FAP-2286 tracer." (PMID 35326670, 2022). "Many clinical trials aim to explore the efficacy and safety of FAP-targeted therapy in various metastatic cancers." (PMID 34112258, 2021). "Regarding clinical trials, the most common target molecule of activated fibroblasts in the treatment of metastatic cancer is FAP." (PMID 34112258, 2021). "Although circulating fibroblasts (FAPα+/ α-SMA+/CK−/CD45−) were found in metastatic cancer patients (median = 4/7.5 ml) using filtration, these cells were not consistently isolated in our studies." (PMID 29657983, 2017). "Intriguingly, although FAP expression has been largely reported in MAFs within collagen‐containing perivascular and septal regions, it was also found in a fraction of metastatic cancer cells, which may complicate the identification of MAFs in scRNAseq analysis based on FAP." (PMID 40908670, 2025).
thyroid cancer (10 papers, 2020 to 2025). "Further research is needed, especially on the promising 18F-TFB and FAP-targeting tracers, to improve thyroid cancer staging and treatment outcomes." (PMID 38611079, 2024). "The following terms were used: “FAP” or “FAPi” or “Fibroblast activating protein” and “thyroid” or “thyroid cancer”, in different combinations." (PMID 38398230, 2024). "These include extracellular matrix (ECM) components, cancer-associated fibroblasts (CAFs) and the expression of the fibroblast activation protein (FAP) known to be involved in immune evasion, disease progression and a worse prognosis of thyroid carcinoma (TC) patients." (PMID 41233863, 2025). "The future direction of FAP-targeted radioligand therapy (FAP-RLT) combines diagnostic imaging with therapeutic potential, showing promise in various cancers, including breast, pancreatic, and thyroid cancers." (PMID 38540204, 2024). "Unsupervised clustering confirmed the target genes (LOX, p16, α-SMA, COL1A1, and FAP) upregulation in thyroid cancers and in particular in those with BRAF-like signaling (115 out of 206 BRAF-like tumors clustered in the 5-genes overexpressing group; p-value < 0.0001)." (PMID 31906302, 2020). "Radionuclide therapy targeting FAP such as 177Lu-EB-FAPI is being investigated and the first-in-human trial for metastatic radioiodine-refractory thyroid cancer was conducted in 12 patients with objective response rate of 25%." (PMID 40741380, 2025). "Analogous to transcriptomic expression analysis, thyroid carcinoma specimens (THCA) were characterized by significantly negative correlation coefficients regarding FAP expression and endothelial cell counts." (PMID 36672341, 2023).
bladder cancer (9 papers, 2020 to 2025). "Previous research has revealed high levels of FAP expression is associated with poor prognosis in patients with colon and bladder cancers." (PMID 40438108, 2025). "In bladder cancer, FAP+ CAFs have been associated with immune cold TMEs with poor infiltration of CD8+ T-cells and with considerable loss of human leukocyte antigen (HLA-I) expression on tumour cells." (PMID 36313650, 2022). "Primary CAFs with high expression of fibroblast activation protein (FAP) were isolated from bladder cancer tissue samples." (PMID 37461061, 2023). "As a further demonstration of the reliability of our findings, we created subcutaneous xenograft models and demonstrated that the TGF-β1/FAP/VCAN axis regulates bladder cancer EMT in vivo." (PMID 37461061, 2023). "Above all, we revealed that the TGF-β1/FAP/VCAN axis promotes stromal fibroblast-mediated EMT in bladder cancer in cytological experiments." (PMID 37461061, 2023). "We revealed a new mechanism whereby TGF-β1 dominated stromal fibroblast-mediated EMT of bladder cancer cells via the FAP/VCAN axis and identified potential biomarkers (FAP, VCAN, N-cadherin, and Vimentin) of bladder cancer." (PMID 37461061, 2023). "For example, bladder cancer sections demonstrated stronger staining with median H-score of 25.0 (38% FAP positive, n = 26) than the TMA cores with 2.5 median H-score (n = 40)." (PMID 35608703, 2022). "When co-expressed with basal markers CK5/6 and CD44, FAP was a strong prognosticator of disease-specific survival in bladder cancer." (PMID 36313650, 2022). "Similar to findings in bladder cancer, we also observed an increase in the levels of FAP, a known CAF marker." (PMID 32751693, 2020). "Stromal fibroblast-mediated EMT was induced in bladder cancer cells by TGF-β1/FAP." (PMID 37461061, 2023). "In addition, we demonstrated that the TGF-β1/FAP/VCAN axis regulates bladder cancer EMT in subcutaneous xenograft models." (PMID 37461061, 2023). "One potential reason for the significantly higher uptake with [68Ga]FAPI-uptake compared to [18F]FDG, might be due to the abundant tumor stroma in bladder cancer with FAP-overexpression of CAFs depending on the tumor stage." (PMID 35349039, 2022). "Versican (VCAN), a downstream molecule of FAP, plays an essential role in TGF-β1/FAP axis-induced EMT in bladder cancer cells." (PMID 37461061, 2023). "The CAFs that we extracted from bladder cancer tissue also showed a significant increase of α-SMA and FAP." (PMID 38001512, 2023).
colorectal tumor (9 papers, 2005 to 2026). "Among the IHC biomarkers expressed in colorectal tumors, FAP, α-SMA, VIM, S100A4, PDGFR-α/β, and POSTN were reported in a general review addressing the question of the significance of CAFs in tumor progression and metastasis." (PMID 41450913, 2025). "We also observe a significant reduction in lung metastases of colorectal tumours through intravenous delivery of our BEVir targeting CEA on tumour cells, in combination with oncolytic VV encoding a TCE targeting FAP on CAFs or αCTLA4." (PMID 36405739, 2022). "Immunofluorescence staining showed α-SMA positive cells and FAP positive cancer associated fibroblasts in the CRC area and the peri-cancerous area, suggesting that stromal fibroblasts in colorectal tumor microenvironment were activated." (PMID 34405010, 2021). "Therefore, we analysed FAP expression in a composite cohort of more than 90 thousand single cells derived from 29 colorectal tumours and adjacent normal tissue with annotated cellular identities." (PMID 35296803, 2022). "We also observe a significant reduction in lung metastases of colorectal tumours through intravenous delivery of our oncolytic virus driven T-cell based combination immunotherapy to target colorectal tumours and FAP-positive stromal cells or CTLA4-positive Treg cells in the tumour microenvironment." (PMID 36405739, 2022). "To validate this tumor-specific fibroblast infiltration, we analyzed the expression of stromal cell subtype markers CD24, CD26, NT5E, FAP, and FGFR2 in colorectal tumor and non-malignant large intestine samples by flow cytometry." (PMID 35365629, 2022).
intrahepatic cholangiocarcinoma (9 papers, 2021 to 2025). A carcinoma that arises from the intrahepatic bile duct epithelium in any site of the intrahepatic biliary tree. "Fittingly, in human intrahepatic cholangiocarcinoma, high expressions of stromal FAP and CCL2 were negatively associated with ICC patient survival." (PMID 34804061, 2021). "In intrahepatic cholangiocarcinoma (ICC), tumor cells located at the leading edge exhibit high proliferative activity and are closely associated with stromal components, including endothelial cells and POSTN+ FAP+ fibroblasts." (PMID 41425545, 2025). "Fibroblast activation protein (FAP)-mediated progression of intrahepatic cholangiocarcinoma (ICC) can be abrogated by anti-Gr-1 antibody treatment, as FAP mediates the infiltration of MDSCs in ICC via inducing CCL2 expression to promote tumor progression and angiogenesis." (PMID 38397901, 2024). "Multiplex-IF of intrahepatic cholangiocarcinoma revealed stromal protein gradients similar to those observed in CRLM, which were characterized by ASMA, NGFR, and PDGFRa at the outer edge, and FAP and PDGFRb at the inner side of the rim." (PMID 37596278, 2023). "However, the effect of high FAP expression in intrahepatic cholangiocarcinoma (IHCC) has not been fully clarified." (PMID 38017374, 2023).
invasive ductal carcinoma (9 papers, 2008 to 2026). "In invasive ductal carcinoma of the breast, a similar positive association between high stromal FAP expression and improved patient survival was observed." (PMID 41410015, 2026). "In invasive ductal breast carcinomas, the expression of FAP was restricted to the stromal cells, and increased FAP expression was an independent prognostic factor associated with better prognosis." (PMID 26828520, 2016). "Immunohistochemical analysis using formalin-fixed and paraffin-embedded sections disclosed expression of FAPα in infiltrating ductal carcinomas (IDC)." (PMID 25593080, 2015). "Clinical observation revealed that the overexpression of FAPα by ductal carcinomas is congruent with the invasion and metastasis of infiltrating ductal carcinomas (IDC) of the breast." (PMID 25593080, 2015). "FAP is found to form a protease complex with dipeptidyl peptidase IV (DPP4), which is another type II transmembrane protein with serine protease activity, at the endothelial cells of capillary-like micro-vessels within invasive breast ductal carcinoma." (PMID 35222418, 2022).
liver cirrhosis (9 papers, 2010 to 2024). "Activated FAP is almost exclusively found in wound healing and pathological conditions such as scar formations, liver cirrhosis, inflammation and cancer." (PMID 36072860, 2022). "Our data is consistent with the study in which plasma soluble FAPα (sFAPα) levels were increased in patients with liver cirrhosis." (PMID 28415791, 2017). "A number of studies indicated a role for FAP in the pathogenesis of chronic inflammatory and fibrotic conditions, such as liver cirrhosis." (PMID 25852817, 2015). "FAP expression typically occurs in fetal mesenchymal tissue, but it is selectively upregulated in reactive stromal fibroblasts within epithelial cancers, dermal scars of healing wounds, and liver cirrhosis." (PMID 38540204, 2024). "Finally, the assay was used to detect elevated FAP activity in human patients diagnosed with liver cirrhosis and to determine the effectiveness of a chemical inhibitor for FAP in mice." (PMID 28970566, 2017).
nasopharyngeal carcinoma (9 papers, 2017 to 2024). A carcinoma arising from the nasopharyngeal epithelium. "In one case, a patient with nasopharyngeal cancer was upstaged with newly emerged nodal metastasis on both sides of the neck, noticed only in the FAP scans." (PMID 35771317, 2022). "Regarding nasopharyngeal carcinoma (NPC), the Epstein–Barr virus can promote fibrosis and NPC progression by activating signaling of YAP1/fibroblast activation protein (FAP) α in fibroblasts." (PMID 38176714, 2024). "Other publications also reported on FAP-specific PET for head and neck tumors, among them the discovery of an occult nasopharyngeal carcinoma in a patient with cancer of an unknown primary (CUP)." (PMID 32942573, 2020). "Notably, in another patient with nasopharyngeal carcinoma, both tracers exhibited similar uptake in several metastatic lung lesions, which demonstrated positive FAP expression and negative integrin αvβ3 expression." (PMID 37142301, 2023).
Obesity (9 papers, 2016 to 2025). Accumulation of substantial excess body fat. "In humans, a successful therapeutic approach that focuses on designing specific inhibitors of FAP to overcome the FGF21-resistant state associated with obesity and type 2 diabetes would succeed." (PMID 31546675, 2019). "However, that the observation that FAP knockout mice are resistant to diet-induced obesity and the metabolic abnormalities associated with obesity indicates that other FAP substrates may be involved in regulating metabolism in mice and remain to be discovered." (PMID 26962859, 2016). "Obesity decreased the FAP population at 3 dpi and prevented FAPs from apoptosis at 7 and 14 dpi." (PMID 36513394, 2023). "For DE RNAs of obesity-related ccRCC in SAT, 4 mRNAs (ENO2, YY1AP1, FAP, IL10RB) and 1 miRNA (hsa-miR-425) were eligible for the following risk score analyses." (PMID 34621242, 2021). "For DE RNAs of obesity in SAT, 4 mRNAs (ENO2, YY1AP1, FAP, IL10RB) and 1 miRNA (hsa-miR-425) were found." (PMID 34621242, 2021).
Crohn disease (8 papers, 2020 to 2026). A gastrointestinal disorder characterized by chronic inflammation involving all layers of the intestinal wall, noncaseating granulomas affecting the intestinal wall and regional lymph nodes, and transmural fibrosis. "FAP+ fibroblasts are identified as a key subtype responsible for pathogenic ECM production in Crohn’s disease-associated intestinal fibrosis." (PMID 39024569, 2024). "In Crohn’s disease, which is a chronic intestinal inflammation that ultimately leads to fibrosis, an increased expression of FAPα has also been found." (PMID 38136590, 2023). "However, the overexpression of FAPα was observed only in strictures (scarred areas) compared to non-stricture areas of the colon in biopsies taken from patients with Crohn’s disease." (PMID 38136590, 2023). "A recent study showed that FAP was also positive in Crohn’s disease." (PMID 36675506, 2023). "Gallium-68 labeled FAP inhibitors (Ga-68-FAPI) used in PET/CT imaging appear to be a promising imaging method to differentiate inflammation from fibrosis and to guide subsequent therapy in patients with stricturing Crohn’s disease; however, further studies are warranted." (PMID 40565806, 2025).
head and neck squamous cell carcinoma (8 papers, 2022 to 2025). A squamous cell carcinoma that arises from any of the following anatomic sites: lip and oral cavity, nasal cavity, paranasal sinuses, pharynx, larynx, and salivary glands. "To provide more supporting evidence that YAP1 and FAPα induce an immunosuppressive T cell phenotype, we interrogated the Cancer Genome Atlas (TCGA) database for correlations between YAP1/FAPα expression and immune regulatory molecules in head-and-neck squamous cell carcinoma." (PMID 35986369, 2022). "Based on the observation that fibroblast activation protein (FAP) is upregulated in cancer-associated fibroblasts (CAFs) infiltrating all solid tumors, including head and neck squamous cell carcinoma (HNSCC), we developed the novel PET/NIR probe [68Ga]Ga-FAP-2286-ICG." (PMID 38026901, 2023). "CAF-focused IMC panels have been validated in the context of breast cancer and head and neck squamous cell carcinoma (HNSCC), resulting in the identification of distinct CAF subtypes, expressing different levels of αSMA and FAP (Fibroblast Activation Protein)." (PMID 40292277, 2025).
acute coronary syndrome (7 papers, 2021 to 2025). Signs and symptoms related to acute ischemia of the myocardium secondary to coronary artery disease. "We have previously shown that current smoking and elevated CRP levels are associated with lower FAP concentrations in patients with acute coronary syndromes." (PMID 40690098, 2025). "This is in contrast to our previous findings in patients with cardiovascular disease, where low FAP concentrations were linked to worse outcomes in patients with acute coronary syndrome and stroke." (PMID 40690098, 2025). "In acute MI, circulating FAP is associated with the risk of death and compared to healthy blood donors, circulating FAP concentrations were reduced in patients with acute coronary syndrome." (PMID 36568546, 2022). "In further studies of atherosclerosis-related conditions, reduced levels of FAP in acute coronary syndromes and coronary heart diseases were observed." (PMID 34638433, 2021). "However, the role of FAP expression by smooth muscle cells in atherosclerotic plaques and in plaque rupture, resulting in acute coronary syndromes, are not well understood." (PMID 40278373, 2025). "Patients with an acute coronary syndrome and a decreased FAP expression may exhibit a poorer prognosis." (PMID 34638433, 2021). "The role of FAP in acute coronary syndromes may exceed the impact on the ECM and plaque stability as fibrinolysis inhibitor α2-antiplasmin was found to be a potential substrate of soluble FAP." (PMID 40278373, 2025).
brain tumors (7 papers, 2020 to 2025). "The sensor is targeted at the fibroblast activation protein (FAP), an extracellular dipeptidase and clinically relevant biomarker of brain tumor biology." (PMID 34931988, 2021). "The presence and possible importance of FAP+ mesenchymal cells in brain tumors is less explored." (PMID 38705944, 2024). "(A) Geometry employed for wide-field molecular imaging of FAP activity in rat brain tumors." (PMID 34931988, 2021). "For primary and secondary brain tumors, it still remains unclear if blood-brain-barrier disruption is a requirement for FAP-enhancement." (PMID 32942573, 2020). "Gene expression data also suggested overexpression of FAP in several paediatric brain tumor types." (PMID 33082953, 2020).
clear cell renal cell carcinoma (7 papers, 2020 to 2026). "In renal clear cell carcinoma, FAP+CAFs are strongly associated with larger tumor diameter (>7 cm), higher grade (G3/4), higher T-stage (pT3/4), tumor necrosis, sarcomatoid transformation, and early lymph node metastasis." (PMID 37277751, 2023). "Herein, we aimed at exploring the FAP expression in clear cell renal cell carcinoma (ccRCC) along with its clinical implication." (PMID 37752545, 2023).